PIM1 (Pim-1 proto-oncogene, serine/threonine kinase)
Diseases named in the same sentence as PIM1 in open-access papers (continued):
Sharing a sentence is not in itself a finding about the gene and the disease.
tumor (continued). "Transcripts coding for tumor-suppressing proteins (Apc, Brca2, and Cdc73) are upregulated while tumor-promoting protein transcripts are downregulated (Met, Junb, and Pim1)." (PMID 32970688, 2020). "Elevated NEK2 and PIM1 expression were related to aggressive tumor phenotype and indirectly affected the overall survival of BP-NEN patients." (PMID 32504181, 2020). "PIM1 activity promotes tumor cell growth and survival through the modification of several cell cycle regulators and apoptosis mediators." (PMID 32504181, 2020). "Since their profound invasive potential was the hallmark of U-87 MG xenografts growing in tissue slice tandem-cultures, we assessed Pim1 inhibitor effects on the tumor invasion index." (PMID 32967361, 2020). "Meanwhile, in triple-negative breast cancer (TNBC), PIM1 inhibition impaired the growth of both cell line and patient-derived xenografts and sensitized tumor cells to chemotherapy, partially via regulating myc and downstream Mcl1." (PMID 30989585, 2019). "PIM1 inhibitor upregulated p27 expression and nuclear accumulation, consequently suppressing tumor formation." (PMID 30989585, 2019). "PIM1 is a novel downstream target of miR‐497‐5p and mediates the tumour‐promoting role of the SNHG16/miR‐497‐5p axis in DLBCL cells." (PMID 31483572, 2019). "The IHC results show that a higher PIM1 and lower RUNX3 level is associated with advanced T-stage, lymph node involvement and nerve invasion that translates to aggressive tumor behavior." (PMID 29467592, 2018). "Proviral integration Moloney virus (PIM) kinases (PIM1, 2 and 3) are overexpressed in several tumour types and contribute to oncogenesis." (PMID 29765150, 2018). "Emerging evidence has shown that the PIM serine/threonine kinase family, including PIM1, PIM2 and PIM3, is associated with tumour progression towards metastasis." (PMID 29472550, 2018). "Photographs of the tumours at necropsy and the measured volumes of the tumours indicated that PIM1-depleated ACHN cells grew much more slowly than control cells." (PMID 29472550, 2018). "Collectively, these results demonstrate that PIM1 functions as a tumour promoter in ccRCC and that depletion of PIM1 dramatically attenuates ccRCC oncogenic properties in vivo." (PMID 29472550, 2018). "Collectively, these data reveal that PIM1 potentially contributes to ccRCC tumour migration, invasion and angiogenesis in vitro." (PMID 29472550, 2018). "SMI-4a is a selective inhibitor of PIM-1 protein and exerts anti-tumor activity in chronic myeloid leukemia cells." (PMID 29483938, 2018). "Treatment with anti-VEGF targeting agents dramatically increases PIM kinase expression, and overexpression of PIM1 effectively blocks the ability of these drugs to prune tumor vasculature." (PMID 30460324, 2018). "In all the tumor tissues overexpressing PIM1/2, we detected a clear increment in the expression of IL-6, while NFAT2 was clearly increased and we observed an increase in two NFAT2 targets, cMYC and OSM." (PMID 28938604, 2017). "Intraperitoneal injection of PEI‐complexed miR‐145 substantially reduced tumor proliferation and increased apoptosis of tumor cells, while miR‐33a decreased oncogenic kinase Pim‐1 and dampened tumor cell proliferation." (PMID 27282910, 2016). "We fully characterized the tumor responses to these genetic alterations in both PIM1 and PIM2 models, corroborating their role as oncogenes by inducing a hyperproliferation state in tissues of the male reproductive system." (PMID 27901106, 2016). "Further studies are needed to investigate the correlation of PIM-1 expression levels between tumour tissue and plasma." (PMID 27596051, 2016). "We fully characterized the tumor response to PIM1/2 overexpression in transgenic mouse models, which corroborated their role as weak oncogenes by inducing a hyperproliferation state in the tissue of the male reproductive system." (PMID 27901106, 2016).
tumor (continued). "In contrast, 37 of 90 tumour-adjacent samples showed low-level PIM-1 protein expression, and 53 of 90 tumour-adjacent samples showed high-level PIM-1 protein expression." (PMID 27596051, 2016). "Upon further investigation using western blot analysis of tumor samples, PIM1 expression was reduced in most shPIM1 tumors, while levels of p27 and cleaved PARP were elevated." (PMID 27448973, 2016). "RNA-sequencing analysis showed that TTP over-expression downregulates several tumor-related factors, including Pim-1 and IL-6." (PMID 26894969, 2016). "We performed functional assays to investigate the effect of modulated PIM1 expression on HCC tumor growth and progression under normoxia and hypoxia." (PMID 25834102, 2015). "In light of the expression pattern of PIM1 by immunohistochemical analysis, we next investigated the tumorigenicity of PIM1 in vivo by comparing the tumor growth using PIM1 knockdown approach." (PMID 25834102, 2015). "The tumor-forming incidence was lower in PIM1 stable knockdown clone (1/4), as compared with NTC (4/4)." (PMID 25834102, 2015). "MiR-328 has been suggested to be a tumor suppressor by targeting proto-oncogene serine/threonine-protein kinase PIM1 and translational regulator protein hnRNP E2." (PMID 26185105, 2015). "The activation of either c-Myc or N-Myc was involved in every tumor, suggesting an oncogenic collaboration between Myc and Pim-1 genes in lymphomagenesis." (PMID 25491234, 2014). "More work is be needed to further elucidate the potential role of this PIM1 activity in other tumor types." (PMID 24919854, 2014). "Conversaly, Eμ-Myc;Eμ-Pim1 mice with low expression of c-Myc were viable and with low tumor incidence." (PMID 25491234, 2014). "In contrast, at protein level, Pim-1 expression was overexpressed in 87.5% (21 of 24) tumor tissues than in adjacent normal tissues." (PMID 25342548, 2014). "MiR-486-5p was downregulated in 87.5% (21of 24) tumor tissues compared with the matched normal lung tissues, whereas Pim-1 protein was upregulated in 87.5% (21 of 24) tumor tissues by Western bolt analysis." (PMID 25342548, 2014). "PhIP increased the number of tumors and reduced the latency of tumor development; surprisingly, this effect was strongest in female Eμ-Pim1 mice." (PMID 24860787, 2014). "In this study, we demonstrated that Pim1 acts as a positive regulator of cellular senescence, which implies that Pim1 likely has characteristics of tumor suppressor." (PMID 25040935, 2014). "High expression of Pim-1 and low expression of RUNX3 were associated with aggressive tumor behavior." (PMID 25551195, 2014). "At mRNA level, Pim-1 was upregulated only in 37.5% (9/24) tumor tissues when compared with the paired normal lung tissues." (PMID 25342548, 2014). "We further compared Pim-1 expression in matched pairs of frozen tumor and normal tissues from 24 NSCLC patients by using qRT-PCR and Western Blot assays." (PMID 25342548, 2014). "In tumor-adjacent mucosa, 63.56% (218 of 343), 29.15% (100 of 343) and 7.29% (25 of 343) of patients exhibited low, medium, and high Pim-1 expression, respectively." (PMID 24116137, 2013). "When tumor stroma was examined 34.99% (120 of 343), 44.61% (153 of 343) and 20.41% (70 of 343) of patients exhibited low, medium, and high expression of Pim-1, respectively." (PMID 24116137, 2013). "Our data demonstrate that pim-1 oncogene activation of tumor-adjacent mucosa is significantly associated with DFS and that higher level of pim-1 expression account for lower DFS." (PMID 24116137, 2013). "We must note that the location of pim-1 in clusters within the nuclei of tumor-adjacent mucosa cells was scored as fairly strong." (PMID 24116137, 2013). "In a multivariable Cox proportional hazards model, tumor status (P=0.015), TNM stage (P=0.000), pim-1 expression in tumor stroma (P=0.000) and pim-1 expression in tumor-adjacent mucosa (P=0.000) were each independently and significantly associated with DFS." (PMID 24116137, 2013).
tumor (continued). "Pim-1 is usually localized on the membrane, cytosol and nucleus of tumor cells, tumor stroma cells as well as tumor-adjacent mucosa cells, as previously reported." (PMID 24116137, 2013). "The three Pim family members Pim-1, Pim-2 and Pim-3 identified in humans have been reported as signalling protein kinases playing an important role in tumor biology." (PMID 23755147, 2013). "Currently available studies have demonstrated that the expression of Pim-1 can be predictive of tumor outcome following chemotherapy and surgery, and it is correlated with the enhanced metastatic potential of the tumor." (PMID 21143989, 2010). "The data also showed effects of Pim1 in promoting tumor proliferation and inhibiting apoptosis in vivo." (PMID 20515470, 2010). "When the tumors were stratified by Non-invasive and invasive, a statistically significant increase of Pim-1 expression was found in the subgroup of invasive tumor when compared with that in the Non-invasive tumor." (PMID 21143989, 2010). "This study examined the role of Pim1 in tumor-induced osteolysis by using SGI-1776." (PMID 40164682, 2025). "Notably, PIM1 and PIM3 were frequently upregulated in GC tumor tissues and have been associated with poor prognosis and increased tumor aggressiveness." (PMID 40992658, 2025). "The degree of PIM-1 overexpression correlates with tumor grade and neoplastic transformation." (PMID 39521748, 2025). "Significantly, our in vivo experiments indicated that SGI-1776, a Pim kinase inhibitor that is particularly effective with Pim1, could protect mice from progressive inflammatory-bone disease and tumor-induced osteolysis." (PMID 40164682, 2025). "PIM1 has been a research hotspot for neoplastic diseases in the past." (PMID 39372407, 2024). "After conducting the necessary in vitro studies, we investigated whether the notable effects of PIM1 knockdown on tumor response to osimertinib could be successfully replicated in vivo." (PMID 39227379, 2024). "None of the patients with the PIM1 p.G28A mutation showed a significant association with clinical parameters, including the patient’s age, sex, tumor location, ECOG performance status, LDH level, IPI score, and Ann Arbor stage." (PMID 38335426, 2024). "PIM1 is a serine/threonine kinase and able to promote tumor growth and drug resistance." (PMID 38993569, 2024). "We further tested the anti-tumor efficacy of combined CDK9/PIM1 inhibition in vivo." (PMID 36998071, 2023). "This suggests that tumor cells surviving initial treatment may over-express Pim-1, given that IL-7 activity leads to JAK/STAT activation." (PMID 36694243, 2023). "Thus, we are seeing a reciprocal regulation of c-Myc/PIM1 and a number of bona fide tumor suppressor miRNAs." (PMID 33946744, 2021). "Selective inhibition of PIM1 leads to defective fatty acid metabolism, which abolishes the immunosuppressive phenotype of tumor-infiltrating myeloid cells and promotes the effector function of anti-tumor CD8 T cells." (PMID 34988072, 2021). "Whether targeting PIM1 alone, or in combination with other potential regulators of GSCs, is sufficient to stop tumor growth in GBM patients remains to be elucidated in future studies." (PMID 34681783, 2021). "In consideration of the fact that stem–like traits were intricately correlated with tumour metastasis, relapse and resistance to chemical agents, we suggested that PIM1 could promote tumour metastasis by facilitating RUNX3 nuclear dislocation." (PMID 32307917, 2020). "Since PIM1 kinases have been shown to drive the growth of PCa, we sought to address whether the PIM1 regulation of H19 levels was also present in this tumor type." (PMID 32146726, 2020). "It hasbeen shown that hypoxia induces Pim-1 expression, which promotessolid tumor growth." (PMID 31359998, 2019).
tumor (continued). "In summary, these results provide new insights into the tumour‐promoting role of the SNHG16/miR‐497‐5p/PIM1 axis in DLBCL progression, which may improve our understanding of the pathogenesis of DLBCL and provide potential therapeutic targets." (PMID 31483572, 2019). "Thus, our data revealed that SNHG16 facilitated tumour growth of DLBCL by targeting the miR‐497‐5p/PIM1 axis." (PMID 31483572, 2019). "Previous studies demonstrated that overexpression of PIM1 could inhibit apoptosis of tumor cells by regulating the cell cycle." (PMID 29467592, 2018). "Furthermore, IHC analysis of the proliferative markers Ki67 and PCNA in tumours from each group revealed that there was limited expression of Ki67 and PCNA in the PIM1-deficient tumour tissues, which indicated slower growth compared to the control tissues." (PMID 29472550, 2018). "Inhibition of PIM1 expression suppresses growth of tumor cells." (PMID 29467592, 2018). "IHC was performed to further quantify the degree of PIM1 depletion in the tumour tissues." (PMID 29472550, 2018). "Importantly, WES and targeted sequencing revealed most mutations were maintained at similar frequencies in PIM1-CBRLuc MFP tumors compared to the patient’s primary tumor biopsy, the P1 parental PDX MFP tumor, and the P3 parental PDX MFP tumor." (PMID 30498242, 2018). "In addition to genes that were also modulated in lSSc samples (i.e., MYC, AKT2, and PIM1), other genes involved in cell proliferation and also in tumor development were overexpressed." (PMID 29559981, 2018). "In addition, IHC for p-Smad2, p-Smad3 and p-c-Myc was performed on the tumour edge tissues of the PIM1 knockdown mice and control mice to confirm tumour invasiveness." (PMID 29472550, 2018). "This suggests that PIM-1 is part of a complex network that regulates tumor progression in AML and elevated PIM-1 expression maybe of prognostic significance to AML patients." (PMID 28851457, 2017). "Patients with high plasma PIM-1 levels had advanced-stage tumours." (PMID 27596051, 2016). "Proviral integration site for Moloney murine leukemic virus (Pim) proteins are a family of serine/threonine kinases composed of three different isoforms (Pim1, Pim2 and Pim3) that are aberrantly expressed in a wide variety of tumor types, including hematopoietic malignancies." (PMID 26956053, 2016). "Using subcutaneous injection of tumor cells in nude mice, knockdown of PIM1 in both HCC cell lines significantly reduced the tumor growth in vivo (Figure 2Aii) in SMMC-7721 and MHCC-97L cell lines, respectively, as compared with their NTC (p=0.003 and 0.036 for SMMC-7721 and MHCC-97L, respectively)." (PMID 25834102, 2015). "We showed previously that tumour onset could be accelerated by retroviral infection and a RIM screen identified a number of candidate third hit genes, including Pim1, a gene that accelerates tumour onset when combined with MYC/Runx2 in the germ-line." (PMID 24586197, 2014). "Generally, the spontaneous tumor rate in Pim1 transgenic mice is low." (PMID 24860787, 2014). "Unexpectedly, in this study, we found that the oncogene PIM-1 expression is induced during senescence and loss of PIM-1 can impair the cellular senescence response in normal fibroblasts, suggesting that PIM-1 probably has properties of a tumor suppressive role." (PMID 25040935, 2014). "By retroviral insertion (MOL4070LTR), pim1 was identified as the most frequently recurring cooperating gene in this system, and elevated levels of pim1 mRNA and protein expression were observed in these neoplasms (B- and T-cell type)." (PMID 24860787, 2014). "The known functions of pim-1 suggest that it may possibly serve as a good marker to evaluate tumor properties, immune activation of tumor interstitial leukocytes, and the cancerous status of the tumor-adjacent mucosa." (PMID 24116137, 2013).
tumor (continued). "Similarly, systemic injection of PEI-complexed miR-33a was validated as a novel therapeutic targeting method for Pim-1, with anti-tumor effects comparable to PEI/siRNA-mediated direct in vivo knockdown of Pim-1 in the model." (PMID 22312290, 2012). "Upregulation of OPN specifically activates the activity of the αvβ3 integrin receptor, which may accelerate tumor angiogenesis and induce the activation of a variety of kinases such as Pim-1, PI3K and AKT." (PMID 23119061, 2012). "The results demonstrated that tumor growth in Pim1-expressing PC3 cells was accelerated compared to control cells, and this could be partly due to c-MYC protein induction." (PMID 20515470, 2010). "However, in Myc transgenic mice harboring Pim-1/− 2 deletion, Pim-3 was activated in tumor cells." (PMID 36694243, 2023). "Furthermore, PIM1 promoted the growth of ccRCC tumours in vivo and tumourigenesis in vitro." (PMID 29472550, 2018). "Furthermore, we discovered a high expression rate of C-MYC, PSTAT3, and PIM1 in PBL tumor cells." (PMID 29029457, 2017). "In addition, the different oncogenic potential of the myc genes was revealed by the average latency period of tumor manifestation; the latency period was 36 days for Eμ-N-myc:Eμ-pim1 mice and 94 days for Eμ-L-myc;Eμ-pim1 mice, but Eμ-c-myc;Eμ-pim1 animals developed pre-B-Cell leukemia prenatally." (PMID 24860787, 2014). "Thus, pim-1 expression in tumor stroma may be an important biomarker reflecting the ability of T or B cells to produce an immune response against the tumor." (PMID 24116137, 2013). "Thus Pim1 expression can further enhance the tumorigenicity of established tumor cells." (PMID 20515470, 2010). "C-Myc induces PIM1, a serine/threonine kinase, and EZH2, a member of PRC2 polycomb repressor complex, by repressing mir26a to promote tumor proliferation and invasion." (PMID 40044981, 2025). "Among the three PIM kinases, PIM1 exhibited a positive regulation on the memory fitness of T cells, while PIM2 negatively modulated their anti-tumor responses." (PMID 41199316, 2025). "Our findings reveal that phosphorylation by PIM1 increases ABI2 protein stability, which leads to stabilization of the WRC and enhances tumor cell protrusive activity and invasion." (PMID 37042842, 2023). "At the same time, the apoptosis-related gene PIM1, proliferation-related gene CCND1, migration- and invasion-related gene BMPR2, and tumor immunocyte infiltration-related gene IFNAR1 also appeared in the core network." (PMID 35241097, 2022). "In vitro and in vivo studies showed that the synergy of PIM1 inhibitors and VEGF-targeting agents led to reduced proliferation, lessened tumor vasculature and decreased metastasis." (PMID 35799213, 2022). "PIM1 is the most studied of the PIM kinase family and while several early studies have shown that tumor PIM1 has a positive impact on patient outcomes." (PMID 33946744, 2021). "Along with PIM1 being overexpressed in DLBCL cells compared to normal B-cells, tumor cells are prevented from undergoing apoptosis inactivating proteins such as apoptosis signaling kinase 1 (ASK1), preventing further activation of FAS ligand." (PMID 34275438, 2021). "In previous studies, HBP1 was described as a tumor suppressor that is activated by p38-MAPK and Pim-1, leading to premature cell decay and apoptosis." (PMID 33794968, 2021). "We strongly believe that PIM-1 overexpression in EpCAM(+) CTC fraction merits to be further evaluated and validated as a non-invasive circulating tumor biomarker in a large and well-defined patient cohort with mCRPC." (PMID 32397108, 2020). "Pim-1, a proto-oncogenic kinase, was increased in NSCLC tissue samples and found to be a target of miRNA-486 in this tumor type." (PMID 31979312, 2020). "The founding member was appropriately termed PIM1 and the product of PIM is a Ser/Thr kinase that promotes tumor progression, transcription, translation, survival, and proliferation." (PMID 31073371, 2019).